FOXP3 (forkhead box P3)
Diseases named in the same sentence as FOXP3 in open-access papers (continued):
Sharing a sentence is not in itself a finding about the gene and the disease.
lepromatous leprosy (4 papers, 2014 to 2023). A chronic communicable infection which is a principal or polar form of leprosy. "Both natural and induced Treg cells were observed in skin lesions and peripheral blood in lepromatous leprosy and the immune suppression observed during the course of the disease was linked to an increased FOXP3 expression." (PMID 27764137, 2016). "According to recent research, FoxP3+ induced Tregs may down regulate T cells to cause antigen-specific anergy associated with lepromatous leprosy." (PMID 37153623, 2023). "Recently, it was revealed that FoxP3+ inducible Tregs producing TGF-β may down regulate T cell responses leading to the characteristic antigen specific anergy associated with lepromatous leprosy." (PMID 26751584, 2016). "Our results indicate that FOXP3+ iTregs with TGF-β may down regulate T cell responses leading to the antigen specific anergy associated with lepromatous leprosy." (PMID 24454972, 2014). "Our study found that PD-1 expressing CD4+CD25+FoxP3+ Treg cells were more prevalent in lepromatous leprosy and tuberculoid patients compared to healthy controls which is consistent with other studies." (PMID 37153623, 2023). "Simultaneously, presence of Th17 related cytokines (TGF-β, IL-6, IL-17 and IL-23) decreased the number of FoxP3+ Treg cells concomitantly increasing IL-17 producing CD4+ cells in lepromatous leprosy." (PMID 26751584, 2016). "The recent discovery of CD25+FOXP3+ cells with regulatory functions (Tregs) in mice and man have made it possible to study their role in the dampening of T cell responses in lepromatous leprosy." (PMID 24454972, 2014). "The present investigation provides evidence for the increase of CD4+ CD25+ FOXP3+ iTreg cells in antigen stimulated PBMC cultures of anergic lepromatous leprosy patients." (PMID 24454972, 2014). "Taken together the data provides evidence for increase in antigen induced iTregs in lepromatous leprosy which bear the signature markers of CD25 and FOXP3 in the CD4 lineage of T cells." (PMID 24454972, 2014).
Listeria monocytogenes infection (4 papers, 2010 to 2025). "Under homeostatic conditions and at the peak of an acute listeria infection, Irf4-/- mice showed a significant reduction of FoxP3+ Treg cells." (PMID 40726986, 2025). "Here, we demonstrated that the deletion of IL-4Rα signalling on Tregs resulted in decreased Foxp3 Tregs and increased survival rates of mice in listeriosis." (PMID 39483462, 2024). "Overall, we provide a new perspective on the Treg-specific function of IL-4Rα signalling in listeriosis, highligting the importance of the stability and quality of Foxp3 Tregs." (PMID 39483462, 2024).
lymphedema (4 papers, 2009 to 2025). Excess fluid collection in tissues, causing swelling. "In contrast, expression of Foxp3, GITR, TGFβ, and CTLA-4, known to be expressed by regulatory T cells, was significantly impaired in patients with lymphedema." (PMID 19381284, 2009). "To determine the role of nTregs in the development of lymphedema, we stimulated PBMCs from CP and INF patients with BmA or PPD for 24 h and examined the mRNA expression of nTreg markers—Foxp3, GITR, TGFβ, and CTLA-4—by real-time RT-PCR." (PMID 19381284, 2009). "Furthermore, as Tregs are known to increase during the development of lymphedema, we examined the infiltration of CD4+Foxp3+ Tregs into lymphedema tissues at each time point." (PMID 39941140, 2025). "Importantly, consistent with previous reports and the experimental models, we could demonstrate the increased FOXP3+ and CTLA4+ cell infiltration in human lymphedema biopsies and the increased CTLA4 expression in the subcutaneous tissue of secondary lymphedema patients." (PMID 39737964, 2024). "Our results show that while Foxp3, GITR, TGFβ, and CTLA-4 are significantly upregulated in patients with asymptomatic infection, there is a significant lack of upregulation in filarial lymphedema patients." (PMID 19381284, 2009).
malignant glioma (4 papers, 2012 to 2026). A grade III or grade IV glioma arising from the central nervous system. "The findings of a previous study indicated that prolonged administration of radiotherapy and temozolomide may exacerbate the immunosuppressive tumor microenvironment in malignant gliomas through upregulating Foxp3." (PMID 41438689, 2026). "Polycomb histone methyltransferease can silence the FOXP3 promoter through the action of its catalytic subunit EZH2, that we and others have found upregulated in GB and malignant gliomas." (PMID 23888189, 2012).
MALT lymphoma (4 papers, 2012 to 2022). An indolent, extranodal type of non-Hodgkin lymphoma composed of small B-lymphocytes (centrocyte-like cells). "They found that CXCR5–CD4+PD1hiICOS+Foxp3– Tph cells co-expressed IL-21 and interferon-γ, but low IL-17 in parotid MALT-lymphoma." (PMID 35755031, 2022). "Our results showed that gastric MALT lymphoma patients responding to eradication therapy had higher number of FOXP3+ cells." (PMID 23284739, 2012). "In addition, the systemic depletion of FOXP3+Tregs in vivo efficiently resulted in the regression of MALT lymphoma." (PMID 30999581, 2019). "FOXP3+ cells could be assessed in all gastric MALT lymphoma cases." (PMID 23284739, 2012). "When compared with human gastritis, the expression of FOXP3+ Tregs, CCL17, and CCL22 was more frequently found in human MALT lymphoma samples." (PMID 30999581, 2019). "The aims of the study were to quantify the number of infiltrating FOXP3+ and CD3+ cells in patients with gastric MALT lymphoma at diagnosis and to study kinetics of these cells and CD20+ tumor cells after treatment and during long-term follow-up." (PMID 23284739, 2012). "In addition, to gain insight into the possible influence of therapy on microenvironment and tumor cells in gastric MALT lymphoma, we evaluated the kinetics of CD3+, FOXP3+ and CD20+ cells by immunohistochemistry after treatment and during long-term follow-up." (PMID 23284739, 2012). "Indeed, higher Foxp3/CD4 cell ratios and the absolute number of Foxp3 cells in GML were previously found to be significantly higher in H. pylori eradication responders compared to non-responders, suggesting that Tregs have a function in regression mechanisms of MALT lymphoma." (PMID 26657504, 2016).
mesothelioma (4 papers, 2017 to 2024). A usually malignant and aggressive neoplasm of the mesothelium which is often associated with exposure to asbestos. "Consistent with the current understanding of their role, we observe that a high number of FOXP3+ T-cells was significantly associated with poorer survival in both morphological subgroups of mesothelioma." (PMID 28817839, 2017). "In murine mesotheliomas, a robust association between percentage of CD4+CD25+Foxp3+ T cells and tumor size has been demonstrated." (PMID 33987190, 2021). "Further, local effector CTL failure in mesothelioma is not mediated by CD4+CD25+FoxP3+ Treg cells, as while Tregs influence CTL responses when tumors are small, other immune suppressor cells (macrophages, in particular) play a major role in inhibiting effector CTL." (PMID 31998326, 2019). "Low CD8+ and low FOXP3+ T-cell densities emerge as prognostic in non-epithelioid mesothelioma." (PMID 28817839, 2017).
prostatitis (4 papers, 2015 to 2025). An infectious or non-infectious inflammatory process affecting the prostate gland. "In this review, we discuss the potential role of P. acnes in the development of BPH and PCa and highlight the importance of regulatory T CD4(+)FoxP3(+) (Treg) and Th17 cells in response to P. acnes infection in the context of both prostate diseases." (PMID 36012113, 2022). "Therefore, in this review, we discuss the potential role of P. acnes in the development of BPH and PCa and highlight the importance of regulatory T CD4(+)FoxP3(+) (Treg) and Th17 cells in response to P. acnes infection in the context of both prostate diseases." (PMID 36012113, 2022).
psoriatic arthritis (4 papers, 2023 to 2024). Joint inflammation associated with psoriasis. "CD8+ Foxp3+ T cells have been identified in cancer and other inflammatory settings, including in the joints of ankylosing and psoriatic arthritis, but have yet to be fully defined in JIA." (PMID 39101538, 2024). "Our previous research demonstrated the effectiveness of small spleen peptides (SSPs) in inhibiting psoriatic arthritis progression, even in the presence of the pro-inflammatory cytokine TNFα, by transforming dendritic cells (DCs) into tolerogenic cells and fostering regulatory Foxp3+ Treg cells." (PMID 38672485, 2024).
renal fibrosis (4 papers, 2017 to 2024). A final common manifestation of a wide variety of chronic kidney diseases characterized by glomerulosclerosis and tubulointerstitial fibrosis. "Worsening renal fibrosis was linked with the loss of CD4+FOXP3+IL-17+ T cells in splenic single-cell suspensions." (PMID 38202170, 2023). "Progressive renal fibrosis was associated with the loss of CD4+FOXP3+IL-17+ T cells in splenic single-cell suspensions." (PMID 28693431, 2017). "The number of CD4+FOXP3+ cells increased steadily, accompanied by the presence of FOXP3+IL-17+ cells, which appeared after 14 days but progressively decreased in number by the 21st day and were associated with renal fibrosis in the UUO mice." (PMID 28693431, 2017). "To verify the expression of PYCARD and Foxp3 on renal fibrosis in vivo, we first established a mouse model of renal fibrosis induced by UUO." (PMID 38343546, 2024). "Findings have observed the conversion of CD4+ forkhead box P3 (FOXP3)+ T regulatory (Treg) cells into T helper 17 cells (Th17), contributing to the progression of renal fibrosis." (PMID 38202170, 2023). "Meanwhile, although the role of HDAC inhibitors in renal fibrosis has been proposed, the involvement of FOXP3+IL-17+ T cells in the improvement of renal fibrosis mediated by HDAC inhibitors had not been described." (PMID 28693431, 2017). "We demonstrated that the number of IL-17+FOXP3+ cells, as well as the severity of renal fibrosis, were decreased with TSA treatment." (PMID 28693431, 2017). "The association between FOXP3+IL-17+ T cells and the attenuation of renal fibrosis by the HDAC inhibitor is not clear." (PMID 28693431, 2017). "We have demonstrated a CD4+FOXP3+ Treg effector differentiation program that yields Th17+ cells that induce TGF-β1 mRNA expression and renal fibrosis in UUO kidneys." (PMID 28693431, 2017). "Thus, we evaluated the role of HDAC inhibitors and FOXP3+IL-17+ T cells in renal tissues from UUO mice and in the propagation of renal fibrosis." (PMID 28693431, 2017).
Salmonella Infections (4 papers, 2010 to 2024). Infections with bacteria of the genus SALMONELLA. "A study of the suppressive potency of Foxp3+T regulatory cells during persistent Salmonella infection in mice indicates the presence of these cells, progressively increasing bacterial burden by delaying the activation of effector T cells." (PMID 39682428, 2024). "Accordingly, we compared the suppressive potency for Foxp3+ Tregs isolated at early (day 5) and late (day 37) time points during persistent Salmonella infection." (PMID 20714351, 2010). "In complementary experiments, the relative suppressive environment dictated by Foxp3+ Tregs during Salmonella infection was further characterized." (PMID 20714351, 2010). "Therefore, we quantified the relative expression of each molecule on Foxp3+ Tregs to explore how the observed shifts in suppression potency from early to late time points during persistent Salmonella infection correlate with changes in their expression." (PMID 20714351, 2010). "The requirement for CD4+ T cells in bacterial clearance during persistent Salmonella infection may reflect contributions from either Foxp3-negative effector or Foxp3+ regulatory T cells (Tregs)." (PMID 20714351, 2010). "Another factor that may influence the control of Salmonella infection in T-bet−/− mice is the effect that T-bet can have on the development of T regulatory cells, in particular a subset that expresses both Foxp3 and T-bet and that has been proposed to regulate Th1 responses." (PMID 32591391, 2020). "Notably, while Salmonella infection did not largely affect the frequencies of RORγt+FoxP3- CD4 T cells in the cecum, their absolute abundance was 2.5-fold higher in eSPF+SFB after infection compared to steady state conditions." (PMID 34566952, 2021).
sarcopenia (4 papers, 2022 to 2025). Progressive decline in muscle mass due to aging which results in decreased functional capacity of muscles. "CD4 + FoxP3 + Tregs infiltrate impaired skeletal muscle, which suggested that sarcopenia may lead to tumor immune escape." (PMID 35923193, 2022). "Additionally, CD4+FoxP3+ Tregs infiltrate damaged skeletal muscles, suggesting that sarcopenia may play an important role in tumor immune escape." (PMID 36969820, 2023). "Immunostaining was performed on resected specimens from 23 healthy participants, excluding patients with osteopenia alone and sarcopenia alone, and 37 patients with osteosarcopenia by comparing the numbers of CD4-, CD8-, FOXP3-, PD-1, and PD-L1-positive cells between the groups." (PMID 40445404, 2025).
soft tissue sarcoma (4 papers, 2021 to 2024). A malignant neoplasm arising from muscle tissue, adipose tissue, blood vessels, fibrous tissue, or other supportive tissues excluding the bones. "Besides, PD-L1 expression was evidently associated with age, high tumor grade of soft tissue sarcoma and had a relationship with FOXP3+ Treg infiltration." (PMID 33754005, 2021). "Similarly, a recent meta-analysis showed that PD-L1 expression was significantly associated with an increased infiltration of PD1-positive cells in bone sarcomas and PD1- and FOXP3-positive cells in soft-tissue sarcomas." (PMID 39273017, 2024).
T-cell leukemia (4 papers, 2012 to 2025). A malignant disease of the T-lymphocytes in the bone marrow, thymus, and/or blood. "We then detected Foxp3 expression in both human T cell leukemia cell line and PBMCs from healthy donors." (PMID 23578365, 2013).
thymic carcinoma (4 papers, 2019 to 2022). Thymic carcinoma (TC) is a type of thymic epithelial neoplasm characterized by a high malignant potential. "We herein report a case of thymic carcinoma with GCs complicated by SjS and examine the expression and distribution of SS-A52 antigen and Foxp3+ Treg cells in the resected specimen." (PMID 33592902, 2021). "In patients with thymic carcinomas, high expression of PD-L1, IDO and FOXP3 Tregs was identified in 36%, 14% and 29% of cases, respectively." (PMID 35757304, 2019). "Analysis of SS-A52, germinal centers, plasma cells, and Foxp3+ Treg in thymic carcinoma has never been reported, and their pathological roles in causing SjS have not been studied." (PMID 33592902, 2021).
trachoma (4 papers, 2008 to 2023). "Furthermore, conjunctival FOXP3 expression is increased in active trachoma, suggesting that regulatory T cells might be present and contribute to tear IL-10." (PMID 37862368, 2023).
tropical spastic paraparesis (4 papers, 2006 to 2016). "HTLV-1+ patients suffering from tropical spastic paraparesis have decreased frequencies of Foxp3+CD4+CD25+ Treg as well as impaired Treg functions." (PMID 16800882, 2006). "These Treg-like ATL cells do not produce IFN-γ contrary to the HTLV-I infected CD4+CD25+ cells in the neuro-inflammatory HTLV-I Associated Myelopathy/Tropical Spastic Paraparesis (HAM/TSP), which display a non-Treg phenotype with decreased expression of Foxp3 and increased levels of IFN- γ." (PMID 23962110, 2013).
viral hepatitis (4 papers, 2011 to 2024). An acute or chronic inflammation of the liver parenchyma caused by viruses. "Another recent study investigated the influence of rs3761547 SNP of FOXP3 in the inflammatory responses accompanying viral hepatitis." (PMID 39117877, 2024). "Patients with chronic viral hepatitis display increased expression of Foxp3 in liver, suggesting that Tregs expansion contributes to persistent infection." (PMID 21772667, 2011). "One study suggested that FOXP3 SNPs (rs2232365, rs3761549, and rs3761548) may have an immunomodulatory influence in patients with chronic viral hepatitis." (PMID 39117877, 2024).
vitamin D deficiency (4 papers, 2014 to 2023). A nutritional condition produced by a deficiency of VITAMIN D in the diet, insufficient production of vitamin D in the skin, inadequate absorption of vitamin D from the diet, or abnormal conversion of vitamin D to its bioactive metabolites. "FOXP3 molecule expression significantly increased in CAT patients having vitamin D deficiency who were given vitamin D replacement." (PMID 27086659, 2016). "Treg cells percentage and their FOXP3 molecule expression were reevaluated after replacement therapy in CAT patients with vitamin D deficiency when they achieved euthyroid status." (PMID 27086659, 2016). "Others have also shown that vitamin D metabolites induce regulatory T cell (Treg) differentiation and FoxP3 expression where seasonal vitamin D deficiency is associated with decreased Foxp3 expression by Tregs and that serum 25[OH]D levels correlate with Treg function." (PMID 25101194, 2014). "Vitamin D deficiency may be a contributor to recurrent pregnancy loss and suggests that the supplementation of women with Vitamin D pre-pregnancy may be protective against URPL via affecting Tregs signature genes, FOXP3 and GITR." (PMID 32429643, 2020).
acute lung injury (3 papers, 2019 to 2025). A condition of lung damage that is characterized by bilateral pulmonary infiltrates (pulmonary edema) rich in neutrophils, and in the absence of clinical heart failure. "Study showed that CD4+CD25+FoxP3+ Treg is a critical effector to protect against transfusion-related acute lung injury (TRALI)." (PMID 32565732, 2020).
amyloidosis (3 papers, 2015 to 2023). A disorder characterized by the localized or diffuse accumulation of amyloid protein in various anatomic sites. "This possibility is further supported by recent findings in the 5XFAD AD mouse model of AD, in which transient depletion of Foxp3+ Tregs, or pharmacological inhibition of their activity, was similarly shown to mitigate amyloid plaque clearance." (PMID 26558367, 2015). "In addition, mice were treated with 27-OHC and inhibitors of RORγt and Foxp3 (Th17 and Treg transcription factors), and the factors involved in Th17/Treg balance and amyloidosis were detected." (PMID 38115100, 2023). "It was shown that inhibition of forkhead box protein P3 (FOXP3)-positive regulatory T cells increased interferon-γ (IFNγ)–dependent leukocyte trafficking to the brain, promoting clearance of Aβ and improving cognitive function in a mouse model of amyloidosis." (PMID 31507408, 2019).
aortic aneurysm (3 papers, 2018 to 2022). A ruptured aneurysm located in the wall of the proximal portion of the descending aorta proceeding from the arch of the aorta. "FOXP3+ Treg cells were abundant in aortic aneurysms, especially in AAA groups and displayed high expression of exhausted genes CTLA4, TIGIT, TNFRSF14, ICOS, and CD28." (PMID 36703732, 2022).
astrocytomas (3 papers, 2022 to 2024). "In addition, FoxP3+ Tregs are most frequently found in GBM and very rarely found in low-grade astrocytomas and oligodendroglial tumors." (PMID 35646697, 2022).